CCDC149 (coiled-coil domain containing 149)
Synonyms: DKFZp761B107
Tractability: PROTAC: its protein half-life has been measured.
Gene: Protein-coding gene on chromosome 4 (24,803,514 to 24,980,204, reverse strand). Ensembl gene ENSG00000181982.
Subcellular location (Human Protein Atlas): Nucleoli
Genetic constraint (gnomAD): Loss-of-function variants: 31 observed, 36.38 expected, observed/expected ratio (o/e) 0.85, 90% interval 0.64 to 1.15. The upper end of that interval is the gene's LOEUF score, 1.15, which puts it in group 5 of 6, group 1 being the genes least tolerant of losing a copy. Missense variants: 475 observed, 541.09 expected, observed/expected ratio (o/e) 0.88, 90% interval 0.81 to 0.95. Synonymous variants: 211 observed, 219.58 expected, observed/expected ratio (o/e) 0.96, 90% interval 0.86 to 1.08.
Homologues: Orthologues: chimpanzee CCDC149 (99% identical), macaque CCDC149 (98% identical), pig CCDC149 (89% identical), guinea pig CCDC149 (88% identical), dog CCDC149 (82% identical), mouse Ccdc149 (81% identical), rabbit CCDC149 (79% identical), rat Ccdc149 (79% identical), tropical clawed frog ccdc149 (62% identical), zebrafish ccdc149b (49% identical), zebrafish ccdc149a (45% identical), Drosophila melanogaster CG14868 (29% identical), and 1 more.
Diseases named in the same sentence as CCDC149 in open-access papers:
CCDC149 is named in the same sentence as 3 diseases in open-access papers, as found by Europe PMC text mining. Sharing a sentence is not in itself a finding about the gene and the disease. The quoted sentences say what the papers report.
thyroid carcinoma (1 paper, 2024). "CCDC149 has recently been identified as a genetic susceptibility gene for thyroid carcinoma." (PMID 38584840, 2024).
cancer (1 paper, 2023). A tumor composed of atypical neoplastic, often pleomorphic cells that invade other tissues. "Moreover, the PT complex upregulated the expression of specific potential cancer suppressor genes, such as cyclin G2, V-set and transmembrane domain containing 4 (VSTM4), coiled-coil domain containing 149 (CCDC149), CD2 molecule, and cyclin G2." (PMID 38027033, 2023).
CCDC149 also shares sentences with these, for which no sentence is quoted: glioma (1 paper).